CCL21 (C-C motif chemokine ligand 21)
Diseases named in the same sentence as CCL21 in open-access papers (continued):
Sharing a sentence is not in itself a finding about the gene and the disease.
colitis (5 papers, 2012 to 2022). Inflammation of the colon. "CCL21 was mainly expressed in the isolated lymphoid follicles (ILFs) of the colon during OXZ colitis." (PMID 34997096, 2022). "CCL21 was mainly expressed around the T cell zone in the isolated lymphoid follicles (ILFs) of the middle colon during OXZ colitis." (PMID 34997096, 2022). "This is partly evidenced by an elevated expression of T-cell chemoattractants such as CXCL9, CXCL11, and CCL21 in colonic epithelial cells in piglets with DSS-induced colitis." (PMID 35898495, 2022). "CCL21 expression correlated with induction of ulcerative colitis in mice, and when that colitis was treated CCL21 expression decreased." (PMID 34197491, 2021). "Several genes encoding chemokines, including CCL21, and 25, and CXCL12, 14, and 15, showed gradually decreased expression during the development of colitis, indicative of a changing chemotactic profile during the progression of colon inflammation." (PMID 23226271, 2012). "A mouse colitis study demonstrated that CCL21 suppression could decrease damage induced by ulcerative colitis, suggesting that CCL21 might be a therapeutic target for UC treatment." (PMID 34456974, 2021). "More importantly, mesalazine treatment reversed the suppressive effect of immune responsive genes, including chemokine (C–X–C motif) ligand (CXCL3), chemokine (C–C motif) ligand (CCL11 and CCL21), chemokine receptor (CXCR2), and colony-stimulating factor (CSF3) in the DSS-induced colitis model." (PMID 34456974, 2021). "Interestingly, the expression of a set of genes encoding chemokines involved in homeostatic processes, including CCL21, CCL25, CCL27 and CCL28, was gradually down-regulated in our TNBS colitis model." (PMID 23226271, 2012).
endometriosis (5 papers, 2007 to 2025). The growth of functional endometrial tissue in anatomic sites outside the uterine body. "C-C motif chemokine ligand 21 (CCL21) is an inflammatory mediator associated with moderate to severe endometriosis; however, to-date, its use as a disease biomarker has failed." (PMID 40698088, 2025). "This study provides novel candidate molecules and suggests a potential local role for CCL16 and CCL21 as mediators contributing to the inflammatory events associated with endometriosis." (PMID 17506907, 2007). "Real-time PCR verified that there were differences in the mRNA encoding CCL16 and CCL21, the two chemokines selected for further study, but that there was considerable heterogeneity in expression in individual endometriosis subjects." (PMID 17506907, 2007). "These combined data clearly show that the expression of CCL16 and CCL21 is disturbed at least in some patients with endometriosis." (PMID 17506907, 2007). "The levels of CCL21 observed in the remaining endometriosis patients ranged from 0.02 – 0.19 fg/pg 18S RNA." (PMID 17506907, 2007). "CCL16 and CCL21 mRNA was confirmed as elevated in some women with endometriosis compared to controls on individual samples." (PMID 17506907, 2007). "Increased expression of CCL21 could suggest that this gene takes part in inducing early inflammatory changes in eutopic endometrium in women with endometriosis and that it continues its role in established lesions." (PMID 40698088, 2025). "Our results showed a directional increase of CCL21 from the endometrium of healthy patients through that of endometriosis sufferers to lesions themselves, indicating its role in the eutopic endometrium inflammation in patients with endometriosis." (PMID 40698088, 2025). "Likewise, the study of genetic polymorphisms of chemokines elucidates an association between rs2812378 and C-C motif chemokine ligand 21 (CCL21) in the advanced stages of endometriosis." (PMID 29503661, 2018). "Further, two novel candidate molecules, CCL16 and CCL21, not previously linked to endometriosis have been validated." (PMID 17506907, 2007). "Furthermore, immunoreactive CCL16 was more intensely stained in epithelium in ectopic endometriosis lesions compared with matched eutopic tissue, and there was a similar trend for CCL21." (PMID 17506907, 2007). "PPI analysis showed that CXCL12 interacts directly with complement C3 and C-C motif chemokine ligand 21 (CCL21), and a previous study showede CCL21 is up-regulated in endometriosis, which acts through inflammatory responses." (PMID 32439908, 2020). "In contrast, in women with endometriosis, eutopic CCL16 and CCL21 mRNA levels were increased in some subjects but with significant patient-to-patient variability." (PMID 17506907, 2007). "CCL21 mRNA was more abundant than that of CCL16 and was markedly elevated in eutopic glands from one endometriosis patient (mean, 0.61 fg/pg 18S RNA)." (PMID 17506907, 2007). "In addition to their upregulation in eutopic endometrium from women with endometriosis, examination of CCL16 and CCL21 in ectopic tissues demonstrated a significant increase in protein relative to expression in eutopic tissue derived from the same individual." (PMID 17506907, 2007). "Unchanged or changed expression (i.e. increased/decreased) in the endometrium from patients with endometriosis was reported for CCL21 with no explanation on how these changes might contribute to the aetiology or pathogenesis of endometriosis." (PMID 31723213, 2019). "How an elevation of CCL21 may contribute to endometriosis is not certain." (PMID 17506907, 2007).
esophageal squamous cell carcinoma (5 papers, 2014 to 2023). Esophageal squamous cell carcinoma (ESCC) is a type of esophageal carcinoma (EC) that can affect any part of the esophagus, but is usually located in the upper or middle third. "Another study discovered that CCL21/CCR7 promoted esophageal squamous cell carcinoma lymph node metastasis." (PMID 36829431, 2023). "CCR7 mRNA was detected in 9/20 esophageal squamous cell carcinoma cell lines with CCL21 activating cell migration and pseudopodia formation." (PMID 35203305, 2022). "In a mouse model of esophageal squamous cell carcinoma, CCL21 activation of CCR7-expressing cells increased cell adhesion that had a higher lymph node metastatic behavior." (PMID 35203305, 2022). "In this study, we hypothesized that patients with esophageal squamous cell carcinoma (ESCC) have a close relationship between CCR7 expression and lymph node metastasis because a functional CCR7 on ESCC cells plays a crucial role in lymph node metastasis in response to CCL21/SLC." (PMID 24766770, 2014).
inflammatory bowel disease (5 papers, 2013 to 2025). A spectrum of small and large bowel inflammatory diseases of unknown etiology. "CCL21 is a chemokine which functions in recruiting T cells and has been associated with inflammatory bowel disease in human and JD in cattle." (PMID 34992636, 2021). "Using this monoclonal antibody, we also demonstrated that CCL21 is expressed in the mucosal venule endothelium of the majority of inflammatory bowel diseases, including Crohn’s disease, ulcerative colitis, and celiac disease." (PMID 34197491, 2021). "Using this monoclonal antibody, we also demonstrated that CCL21 is expressed in the mucosal venule endothelium of the large majority of inflammatory bowel diseases (IBD), including Crohn’s disease, ulcerative colitis, and also in celiac disease." (PMID 34197491, 2021).
oral squamous cell carcinoma (5 papers, 2021 to 2025). "A CC chemokine receptor 7 (CCR7) and CCL21 are abundant in oral squamous cell carcinoma (OSCC) tissues, where they regulate EMT process and promote OSCC desiccation through activation of the JAK2/STAT3 signaling pathway." (PMID 34421979, 2021). "Similarly, CCL21 has been shown to enhance migration, invasion, tumor sphere formation, and colony formation in oral squamous cell carcinoma." (PMID 39859340, 2025). "For example, CCR7 and its ligand chemokine ligand 21 (CCL21) promote the EMT and up-regulate the stemness of oral squamous cell carcinoma by activating the JAK2/STAT3 signaling pathway." (PMID 35538537, 2022). "For example, in oral squamous cell carcinoma, the CCL21/CCR7 axis activates the JAK2/STAT3 signaling pathway to regulate the progression of EMT and promote the stemness of oral squamous cell carcinoma." (PMID 33788424, 2021). "Similarly, oral squamous cell carcinoma expresses CCR7, and CCL21‐mediated signaling leads to lymphatic metastasis, correlating with poor prognosis." (PMID 40038879, 2025).
pulmonary fibrosis (5 papers, 2010 to 2024). Chronic progressive interstitial lung disorder characterized by the replacement of the lung tissue by connective tissue, leading to progressive dyspnea, respiratory failure, or right heart failure. "Bleomycin-induced pulmonary fibrosis in mice involves CCL21 induction, with chemotactic responses of CCR7+ bone marrow progenitor cells, and Ccr7-/- mice are protected from fibrosis." (PMID 39768150, 2024). "Fibroblasts expressing CCR7 exhibit activation and chemotactic responses to CCL21, suggesting a role in orchestrating pulmonary fibrosis development." (PMID 39768150, 2024). "In IPF, fibroblast overexpression of CCR7, induced by CCL21, suggests a role in pulmonary fibrosis development." (PMID 39768150, 2024). "Adoptive transfer of nonspecific interstitial pneumonia fibroblasts into SCID mice caused diffuse interstitial fibrosis, and systemic immunoneutralization of CCR7 or Ccl21-attenuated pulmonary fibrosis." (PMID 39768150, 2024). "CCL19 and CCL21, typically homeostatic, are induced in pulmonary samples from IPF patients and during inflammatory and fibrogenic phases in bleomycin-induced pulmonary fibrosis in mice, indicating common fibrotic pathways between humans and mice." (PMID 39768150, 2024).
asthma (4 papers, 2021 to 2025). "The serum levels of CCL21 and other inflammatory cytokines were analyzed in patients with asthma (n=44) and healthy controls (n=35) by enzyme-linked immunosorbent assay." (PMID 33503170, 2021). "This study aimed to investigate the association between serum CCL21 levels and asthma control." (PMID 33503170, 2021). "Serum CCL21 levels were lower in patients with asthma (254.78±95.66 pg/mL) than in the healthy controls (382.95±87.77 pg/mL)." (PMID 33503170, 2021). "A multiple unpaired Student’s t-test was performed to analyze the differences in CCL21 and interleukin levels between patients with asthma and healthy controls." (PMID 33503170, 2021). "The correlation between serum CCL21 levels and pulmonary function suggests that CCL21 can predict asthma control in patients, but further research is still required." (PMID 33503170, 2021). "Because these ligands interact with CCR7, the serum levels of dissociated CCL21 were lower in patients with asthma than in healthy controls." (PMID 33503170, 2021). "At the same time, we measured and found lower serum CCL21 levels in patients with asthma than in healthy controls." (PMID 33503170, 2021). "We next analyzed the relationship between serum CCL21 and IgE levels and eosinophil counts in asthma patients." (PMID 33503170, 2021). "Serum CCL21 levels were lower in patients with asthma (254.78±95.66 pg/mL) than in healthy controls (382.95±87.77 pg/mL) (p<0.001)." (PMID 33503170, 2021). "We analyzed the relationships between CCL21 levels in asthma patients and their ACT scores, lung function parameters, and FENO." (PMID 33503170, 2021). "In conclusion, we found that serum CCL21 levels may serve as a biomarker for asthma control in clinical studies, but further studies of the specific molecular mechanisms are needed to verify this hypothesis." (PMID 33503170, 2021). "Finally, we assessed the relationship between serum CCL21 and IgE levels and eosinophil counts in patients with asthma." (PMID 33503170, 2021). "However, the specific relationship between CCL21 and DCs in asthma requires further exploration at the cellular level." (PMID 33503170, 2021). "Hence, we found that the serum CCL21 levels in patients with asthma were lower than those in healthy controls, and CCL21 levels were negatively correlated with serum IgE levels and eosinophil counts, which was consistent with previous research." (PMID 33503170, 2021). "Serum CCL21 levels may be a new biomarker for assessing asthma control." (PMID 33503170, 2021). "In this study, we examined the serum levels of CCL21, IL-1β, IL-6, and TNF-α in patients with asthma and healthy controls." (PMID 33503170, 2021). "We also analyzed the relationships between CCL21 levels and the ACT score, pulmonary function parameters, and FENO in patients with asthma." (PMID 33503170, 2021). "The overall eosinophil levels were higher in patients with asthma, and they expressed CCR7 on their surface; all these factors influence serum CCL21 levels in patients with asthma." (PMID 33503170, 2021). "In this study, for the first time, we found that CCL21 levels in patients with asthma were lower than those in healthy controls, and the levels of IL-1β, IL-6, and TNF-α were higher in patients with asthma than in healthy controls." (PMID 33503170, 2021). "It has previously been shown that in vivo neutralization of CCL21 could prevent human DC migration to the cervical lymph nodes in mucocutaneous lymph node syndrome in humanized severe combined immunodeficient mice and the subsequent development of asthma features." (PMID 33503170, 2021). "The role of DCs in the pathogenesis of asthma has been studied, but the effects of CCL21 on DCs and the pathogenesis of asthma are not clear." (PMID 33503170, 2021). "Moreover, the CCL21 levels were significantly different between the not well-controlled asthma, poorly controlled asthma, and well-controlled asthma subgroups." (PMID 33503170, 2021).
B-cell chronic lymphocytic leukemia (4 papers, 2015 to 2025). "CCR7/CCL21 can promote the invasion and metastasis ability of B-cell chronic lymphocytic leukemia cells by activating phosphoinositide-3 kinase and the Rho effector molecule Rho-associated coiled-coil forming protein kinases (ROCK)." (PMID 33158173, 2020). "On the other side, some studies indicated that CCR7/CCL21 interaction regulates MMP9 gene transcription by regulating Extracellular signal-related kinase (ERK)-effector c-Fos (AP1 complex) in B-cell chronic lymphocytic leukemia cell." (PMID 30781353, 2019).
brain tumors (4 papers, 2020 to 2025). "This different response of microglial cells and macrophages to CCL21 suggests that this chemokine could be important for the differential activation of microglia-derived and monocyte-derived TAMs in the context of brain tumors." (PMID 37314567, 2023). "In summary, our study demonstrates the roles of dorsal MLVs in intracranial tumor fluid drainage and immunity, and shows that the MLV remodeling induced by brain tumors is critical for immunotherapy, mainly through a VEGF-C/CCL21 signaling pathway." (PMID 32094452, 2020).
carotid atherosclerosis (4 papers, 2017 to 2023). A thickening and loss of elasticity of the walls of carotid arteries that occur with formation of atherosclerotic plaques. "Elevated levels of circulating CCL19 and CCL21 can be found in patients with unstable angina pectoris compared to controls and enhanced levels of these chemokines were also observed in patients with carotid atherosclerosis, both systemically (CCL21) and within the lesion (CCL19 and CCL21)." (PMID 35600479, 2022). "We discovered that CCL21 was downregulated, and that its receptor, CCR7, was upregulated in preeclamptic placentae, which was consistent with the findings of carotid atherosclerosis." (PMID 36829431, 2023). "The current findings suggest that CCR7 is immunohistochemically localized to macrophages and vascular SMCs via carotid atherosclerosis and highlight that although CLL19 and CCL21 are signaling through CCR7, they may have different effects on macrophages and SMC." (PMID 34777635, 2021).
chronic hepatitis C (4 papers, 2016 to 2023). "One study reported that CCL21 expression during chronic hepatitis C is implicated in the recruitment of T lymphocytes and may promote fibrogenesis via the activation of CCR7 on hepatic stellate cells (HSCs)." (PMID 37296834, 2023). "Neo-lymphoid follicles expressing CCL19 and CCL21 are encountered in chronic inflammatory liver diseases, such as PBC, PSC and chronic hepatitis C." (PMID 37108648, 2023). "Expression of CCL21 was also involved in the organization of inflammatory lymphoid tissue and the recruitment of T-cells, which may promote fibrogenesis via activation of chemokine receptor 7 (CCR7) on HSCs during chronic hepatitis C." (PMID 29137226, 2017).
Ewing sarcoma (4 papers, 2016 to 2024). A small round cell tumor that lacks morphologic, immunohistochemical, and electron microscopic evidence of neuroectodermal differentiation. "Since a high-CD8+ T cells infiltration was associated in Ewing sarcoma with a better outcome, we correlated CCL21 RNA expression levels in therapy-naïve tumor samples with development of metastases, survival and chemotherapeutic response." (PMID 27369431, 2016). "CCL21 expression was significantly higher in Ewing sarcoma tissue samples compared to cell lines (P < 0.01), implying the involvement of a stromal factor." (PMID 27369431, 2016). "CCL21 activation-based immunotherapy was successful in preclinical studies in other tumor types; therefore, we investigated CCL21 expression in Ewing sarcoma as potential target for immunotherapy." (PMID 27369431, 2016). "The CCL21 RNA expression was determined in 21 Ewing sarcoma cell lines and 18 primary therapy-naive Ewing sarcoma samples." (PMID 27369431, 2016). "Only one of twenty-four Ewing sarcoma patient tissues was positive for CCR7 or CCL21." (PMID 35203305, 2022). "The observed positive correlation with survival implies that CCL21 might be a potential prognostic marker for Ewing sarcoma and marks the potential of CCL21 immunotherapy for use in Ewing sarcoma." (PMID 27369431, 2016). "In conclusion, CCL21 is expressed in clinical Ewing sarcoma samples by nontumor-infiltrating immune cells." (PMID 27369431, 2016). "Protein expression analysis of CCL21 and its receptor CCR7 in 24 therapy-naïve tumors showed that there was no expression in all bar one Ewing sarcoma cells." (PMID 27369431, 2016).
heart failure (4 papers, 2012 to 2021). Inability of the heart to pump blood at an adequate rate to meet tissue metabolic requirements. "However, HD patients have a 1.6-fold higher frequency of Tregs compared to BP and a 2.6-fold increase in CCL21, a CCR7 ligand that is known to be related to vascular inflammation and heart failure." (PMID 34941677, 2021).
metastatic tumors (4 papers, 2015 to 2022). "In EwS, high expression of TWIST1 and Xg was found to be positively correlated with poor survival outcomes, whereas low expression of CCL21 was observed in patients with metastatic disease and thus the expression level of CCL21 is negatively correlated with the patient survival." (PMID 36230825, 2022). "Expression of chemokines and their receptors, such as CXCL12/CXCR4 and CCL21/CCR7, in both primary and metastatic tumors suggest that chemokine receptor-bearing cells actively enter the circulation and home to metastatic sites." (PMID 25909600, 2015). "Chemokine CCL21 can induce the migration of antigen-presenting dendritic cells from the interstitium to the lymphatic system, and another study indicated that tenascin-C enhanced an immunosuppressive lymphoid stroma through CCL21/CCR7 signaling, leading to an increase in metastatic tumors." (PMID 34177903, 2021).
renal fibrosis (4 papers, 2020 to 2025). A final common manifestation of a wide variety of chronic kidney diseases characterized by glomerulosclerosis and tubulointerstitial fibrosis. "The blockade of CCL21/mCCR7 signaling by anti-CCL21 mAbs reduced the renal fibrosis." (PMID 40028039, 2025). "It was shown that anti-CCL21 therapy successfully suppresses the infiltration of bone-marrow-derived fibroblasts (CD45+/ColI+) and reduces renal fibrosis." (PMID 39234304, 2024).